IL2 (interleukin 2)
Diseases named in the same sentence as IL2 in open-access papers (continued):
Sharing a sentence is not in itself a finding about the gene and the disease.
COVID-19 (continued). "IL-2 and IL-17A were independent risk factors that could lead to liver injury in coronavirus disease 2019 (COVID-19) patients at admission." (PMID 35401547, 2022). "COVID-19 disease severity is associated with high plasma level of IL-2, which may be considered therapeutic targets for COVID-19 to combat hyperinflammatory responses and cytokine storms." (PMID 34677780, 2022). "Moreover, high serum levels of cytokines, such as IL-6, CCL2, CXCL8, CXCL10, IL-2, and IL-10 were associated with COVID-19-related encephalopathy and showed an enhanced systemic inflammatory response." (PMID 36232655, 2022). "In COVID-19, IL-2 levels are known to be associated with mild and asymptomatic conditions." (PMID 36561720, 2022). "Also, they found that the early increase in inflammatory cytokine IL-2 was associated with faster viral clearance and early immune responses in asymptomatic COVID-19 patients." (PMID 35497875, 2022). "Summarizing, IL-2R expression and IL-2 response may be implicated in the pathophysiology of COVID-19." (PMID 34001199, 2021). "Moreover, we found that IL-2 was an independent risk factor for lung GGOs in patients with moderate-to-severe COVID-19." (PMID 33967617, 2021). "Moreover, higher levels of IFNγ TNFα, IL-2, and IL-10 have been associated with COVID-19 severity, further supporting a pathogenic role." (PMID 33634100, 2020). "This may be due to increased expression of cytokines, including interleukin (IL)-2, IL-6, IL-7, tumor necrosis factor, granulocyte colony-stimulating factor, interferon-gamma, and free radicals associated with the severity of COVID-19." (PMID 32953353, 2020). "Cytokines such as IL-2, IL-6, TNF-α, IFN-γ, and IL-10 could serve as predictors for early prediction of the severity of COVID-19; hence, this study aimed to evaluate the association of cytokine levels IL-2, IL-6, TNF-α, IFN-γ, and IL-10 with the severity of COVID-19 in Bangladesh." (PMID 38707035, 2024). "CBD was also shown to reduce interleukin (IL)-2, IL-1α and β, interferon gamma, inducible protein-10, monocyte chemoattractant protein-1, macrophage inflammatory protein-1α, and tumor necrosis factor-α – all of which are associated with the pathology of severe cases of COVID-19." (PMID 36844029, 2023). "COVID-19 has been associated with an exuberant activation of the host immune system and the excessive production of proinflammatory cytokines, such as IL-1, IL-2, IL-6, IL-10, IL-12, IFN-γ, TNF-α, among others, which may cause tissue injury, particularly on the lungs." (PMID 35090394, 2022). "Moreover, antidepressant use has been associated with a reduced risk of intubation or death in hospitalized patients with COVID-19 because the inhibition of ASM decreases pro-inflammatory mediators such as IL-2, IL-6, IL-7, IL-10, TNF-α, C-reactive protein (CRP), and D-dimer." (PMID 34579284, 2021). "Individuals with either flu-like symptoms or infected with COVID-19 residing in EA exhibited higher production of IL-12p70, IL-6, IL-1β, IL-2, and IL-1ra compared to NEA residents." (PMID 40165959, 2025). "The study aimed to assess the blood IL-2 and IL-7 concentration in relation to the obtained cellular and humoral response in adults six months after vaccination against COVID-19." (PMID 41305439, 2025). "The study aims to assess the blood IL-2 and IL-7 concentration in relation to the obtained cellular and humoral response in adults, six months after vaccination against COVID-19." (PMID 41305439, 2025). "Further study on the contribution of IL-2 and IL-7 to immune response effects of vaccination against COVID-19 is needed." (PMID 41305439, 2025). "Activation of CD8+ and CD4+ T-cells, as well as the generation of TNF-α, IFN-γ, and IL-2, appears to be a significant effect of COVID-19 vaccinations." (PMID 39931582, 2025).
COVID-19 (continued). "Our most significant findings include the association of double mutant alleles (AA) of rs4646140 and rs2074192 in the ace2 gene with decreased IL-6 and IL-2 expression levels respectively in TB-COVID-19 participants." (PMID 40196114, 2025). "A randomized, double-bind, placebo-controlled, parallel trial revealed that additional oral arginine supplementation in patients with COVID-19 led to significantly reduced levels of pro-inflammatory IL-2, IL-6, and IFN-γ." (PMID 40332615, 2025). "Despite the fact that the subject of research is IL-2 and IL-7 concentrations, there are few publications dealing with the post-vaccination response against COVID-19." (PMID 41305439, 2025). "Concerning systemic immunity in COVID-19, clinical studies have shown a significant rise in pro-inflammatory cytokines and chemokines (IL-1β, IL-2, IL-6, IL-8, IL-15, IFN-γ, TNF, MCP-1), characterizing cytokine release syndrome (CRS) or cytokine storm." (PMID 40572294, 2025). "In hospitalised COVID-19 patients, an increased frequency of IL-2 producing CD4+CD45RO+ memory T cells was observed, indicating a persistent CD4+ T cell-mediated immune response." (PMID 40242761, 2025). "In cases of severe or critical COVID-19, the use of dexamethasone, interleukin-2 or interleukin-6 inhibitors, or Janus kinase inhibitors is recommended, alongside optimal supportive and intensive care." (PMID 41155576, 2025). "In COVID-19 patients, IL-2 levels are elevated compared to healthy controls, contributing to severe inflammatory responses and cytokine storms." (PMID 41194029, 2025). "Altogether, this evidence supports the use of IL-2 as a valuable biomarker for assessing both the cell-mediated and antibody response to COVID-19 vaccination in PwMS." (PMID 41246331, 2025). "Virus-neutralizing antibodies, determined in live-virus neutralization assays, were detected in sera from 93% COVID-19 patients, and neutralizing titers correlated with IL-2+ T cell reactivity against spike SI and SII." (PMID 40191213, 2025). "COVID-19 induces uncontrolled inflammation, a so-called cytokine storm, including IL-6, IL-1b, IL-2, IL-10, TNF-α and monocyte chemoattractant protein (MCP-1)." (PMID 38732160, 2024). "A number of cytokines signal through the JAK-STAT pathway, including IL-6, IL-2, IL-15, and IL-10, which are elevated in patients with COVID-19." (PMID 39599762, 2024). "Previous reports have signaled that IL-2-secreting cells are less frequent in those with mild disease compared to those with severe or moderate forms of COVID-19." (PMID 38932392, 2024). "Enrichment analysis showed influence of analyzed miRNAs on IL-2 signaling pathway and multiple cardiovascular diseases through COVID-19-related targets." (PMID 38866792, 2024). "It improves diabetic complications and T cell function in patients with COVID-19 by reprogramming dendritic cell metabolism, inducing tolerance, and reducing pro-inflammatory factors such as IL-2 and tumor necrosis factor alpha." (PMID 39845945, 2024). "Prebooster SARS-CoV-2-specific mBc and IL-2- producing T cells accurately predicted Nab seroconversion (AUC, 0.828) and protection against severe COVID-19." (PMID 39439787, 2024). "In an individual concerned with COVID-19, it is diagnosed as the increase of IL-2 IL-7, along with other interleukins and chemokines." (PMID 37742314, 2024). "The newly reported genetic variant of ACE2 showed a positive correlation with CD40L, IL-1β, IL-2, IL-15, and IL-17A in COVID-19 patients." (PMID 38855114, 2024). "In our study, an increased response of both IFN-γ and IL-2 cytokines was seen in convalescent individuals, in comparison to acute COVID-19 patients." (PMID 38212416, 2024). "PLWH with COVID-19 with a detectable VL had significantly lower concentrations of IL-2, IL-4, IFN-γ, IL-20, IL-22, IL-35, and IL-12p40 than PLWH with COVID-19 with an undetectable VL." (PMID 39597537, 2024).
COVID-19 (continued). "Similar to the acute phase, higher levels of IL-2 and IL-17 are observed in individuals with long COVID-19." (PMID 39188722, 2024). "Age exhibited negative correlations with levels of pro-inflammatory cytokines, including IFN-γ, TNF, IL-2, and IL-6, following COVID-19 vaccination." (PMID 38909235, 2024). "The percentage of CD4+ Tsens was negatively correlated with spike-specific antibody titers, neutralization ability, and COVID-19 reactive IL-2+CD4+ T cells." (PMID 38377029, 2024). "Patients with COVID-19 who are undergoing cytokine storm demonstrate elevated serum levels of IL-2, which serves as an immunopathologic attribute." (PMID 38967887, 2024). "This study aimed to evaluate the association of the levels of cytokines interleukin (IL)-2, IL-6, tumor necrosis factor-alpha (TNF-α), interferon-gamma (IFN-γ), and IL-10 with the severity of COVID-19 in Bangladesh." (PMID 38707035, 2024). "Although the source of IL-2 remains elusive, these studies hint at the crucial role of IL-2 in developing CRS in patients with severe COVID-19." (PMID 39359733, 2024). "Regulation of adaptive immune response was the top enriched activated pathway in our COVID-19-infected cohort compared to controls, suggesting the involvement of cytokines with immune regulatory potential, including IL-2." (PMID 38375062, 2024). "This study identified 30 nodes associated with cytokine storm, ARDS, and inflammatory process of COVID-19, namely, IL-6, IL-6R, NF-κB, IL-2, IL-2RA, IFNA2, IFNAR1, COX5A, and COX411." (PMID 39640429, 2024). "Using the REAC pathway analysis of differentially expressed genes in COVID-19-positive cases, we detected interleukin IL-2, IL-7, and IL-10 as well as IL-1, IL-4, IL-13, and IL-36." (PMID 38240884, 2024). "In this study, we assessed IFN-γ and IL-2 released by T-cells from COVID-19 patients and from vaccinated as well as unvaccinated uninfected individuals." (PMID 38212416, 2024). "Acute COVID-19 patients had a slightly higher rate of positive IFN-γ responses than IL-2 [61.9% (34/55) IFN-γ vs 56.4% (31/55) IL-2; and 65.4% (36/55) had at least a positive result for one of the two cytokines (p = 0.66)]." (PMID 38212416, 2024). "We show that the plasma concentrations of the pro-inflammatory cytokines IL-6 and IL-2 are elevated in severe COVID-19 and were the primary cytokines that distinguished COVID-19 patients who died from those who survived." (PMID 39345212, 2024). "Among various cytokines involved in the CRS of patients with COVID-19, IL-2 has drawn our particular attention." (PMID 39359733, 2024). "In the present pilot study, we evaluated the potential of modulation of the IL-6 (colchicine), IL-17 (ixekizumab), and IL-2 signaling pathways to treat moderate to critical COVID-19 in hospitalized patients." (PMID 37075454, 2023). "A meta-analysis study showed marked elevations in inflammatory markers such as ESR, CRP, serum ferritin, and IL-2, -6, and -10 in patients with severe COVID-19, which were also noted in this study." (PMID 37398817, 2023). "One clinical study has been filed for the delivery of low-dose recombinant IL-2 to patients with COVID-19 as an additional treatment approach to manage ARDS and severe inflammatory response by increasing and stimulating Tregs." (PMID 36679947, 2023). "To investigate the specific regulation of the 41 identified IL2-AIS constituent genes in COVID-19 patients, we initially compared COVID-19 patients with healthy controls in the COMBAT cohort." (PMID 37700317, 2023). "Amongst those with acute COVID-19, eleven markers significantly differed across disease severity categories: IL-1β, IL-2, IL-6, IL-10, IL-18, IL-23, IL-33, TNF-α, IP-10, G-CSF and YKL-40." (PMID 37063871, 2023). "A summary analysis of 182 children hospitalized with COVID-19 had a high proportion of serum interleukin IL-2 and IL-6." (PMID 36982944, 2023).
COVID-19 (continued). "Our findings suggest that the lower expression of the IL2-AIS in community COVID-19 patients likely reflects a more general alteration of the transcriptional profile of cells after the onset of acute symptoms." (PMID 37700317, 2023). "Individuals affected by COVID-19 who need treatment in intensive care units usually have high levels of interleukin (IL)-2, IL-7, IL-10, tumor necrosis factor α (TNF-α), and other pro-inflammatory and also anti-inflammatory cytokines." (PMID 37408184, 2023). "The overexpression of CRP, ferritin, LDH, TNF-α, IL-1β, IL-6, IL-2, IFN-γ, and vascular endothelial growth factor (VEGF) can be associated with COVID-19 severity." (PMID 37654571, 2023). "A study conducted with patients with severe COVID-19 at the beginning of the pandemic demonstrated the potential of the use of low doses of IL-2 due to its immunomodulatory effect." (PMID 37075454, 2023). "Ixekizumab, colchicine, and IL-2 were demonstrated to be safe but ineffective for COVID-19 treatment." (PMID 37075454, 2023). "In contrast, MBL and IL-2 showed decreased expression in patients with moderate COVID-19 symptoms (C2M), while they exhibited higher expression in the severe subtype (C2S)." (PMID 37949890, 2023). "The cytokines TNF-α, IFN-γ, IL-6, IL-2, and IL-10 quantified in newborns of mothers with COVID-19 showed high levels of expression compared with the control group." (PMID 36979888, 2023). "There is controversial literature about the effects of the interleukin-2 (IL-2) cytokine family in COVID-19 pathogenesis and immunity." (PMID 37649897, 2023). "Further work will therefore be necessary to support the potential clinical application of low-dose IL-2 in convalescent COVID-19 patients, including the retrospective analysis of the incidence of PASC in cohorts of patients treated with low-dose IL-2." (PMID 37700317, 2023). "Considering the evidence on the effects of IL-2 in viral infections, this study aims to review the molecular mechanisms and immunomodulatory effects of IL-2 in COVID-19 and its targeting agents." (PMID 37649897, 2023). "However, some studies have suggested that IL-2 levels may differ in different COVID-19 variants." (PMID 37649897, 2023). "Among COVID-19 donors, IL-2, and IL-12(p70) were significantly elevated in PLWH compared to HIV-uninfected participants." (PMID 38343437, 2023). "A significant number of genes related to inflammation, such as IFN-γ and -α responses; TNFA, IL-6, and IL-2 pathways; inflammatory response; and allograft rejection, were highly enriched in COVID-19 kidneys compared with healthy controls." (PMID 36749641, 2023). "In one study of 52 individuals infected with COVID-19, the maximum concentrations of plasma cytokines (IL-2, IL-5, IL-17, IL-8, IL-10, IL-6, IL-12p70, and IFN-γ) were found to be significantly higher in those who had died than in those who had survived." (PMID 36766961, 2023). "Such investigations led to the registration of a clinical trial to examine the effectiveness of low-dose IL-2 in the management of COVID-19 patients with ARDS." (PMID 36992283, 2023). "Acute COVID-19 children had significantly elevated levels of cytokines, IFNγ, IL-2, TNFα, IL-1α, IL-1β and IFNα in comparison to convalescent children." (PMID 37013538, 2023). "Analysis of the dynamics of the transcriptional changes following SARS-CoV-2 infection in both COVID-19 cohorts revealed a progressive modulation of the IL2-AIS genes." (PMID 37700317, 2023). "Convalescent COVID-19 children had elevated levels of IFNγ, IL-2, TNFα, IL-1α, IL-1β, IFNα, IFNβ, IL-6, IL-12, IL-17A, IL-10 and G-CSF in comparison to control children." (PMID 37013538, 2023). "The current study also assessed the relationship of polymorphisms of the cytokine genes IL2, IL6, and IL10 with the severity of COVID-19 in Kazakh population." (PMID 37390087, 2023).
COVID-19 (continued). "Clinical studies have found that COVID-19 intensive care patients exhibit significantly elevated serum pro-inflammatory cytokine levels; interleukin 2 (IL-2) is the one of the typical cytokines." (PMID 38258172, 2023). "In patients admitted to medical emergencies with a confirmed diagnosis of COVID-19, it is important to perform a joint evaluation of demographic characteristics, clinical parameters, interleukins (IL-2, IL-6, IL-7, IL-10, IL-17) and sP-selectin." (PMID 36835858, 2023). "We also report that the cytokine response was more diverse in COVID-19 patients, which is highlighted by IL-2, IL-4, and IL-20 signaling, while HIV-1+ individuals primarily exhibited high levels of NF-kB signaling." (PMID 36992700, 2023). "We found that the EVs of COVID-19 patients contained higher levels of IL-6, TNFα, IL-2, and INFΥ compared to HCs." (PMID 36982991, 2023). "During the stage of systemic inflammation in COVID-19, there is a significant increase in inflammatory biomarkers like IL-2, IL-6, and CRP, which are dramatically enhanced." (PMID 38106427, 2023). "Convalescent COVID-19 children had elevated levels of IFNγ, IL-2, TNFα, IL-1α, IL-1β, IFNα, IFNβ, IL-6, IL-12, IL-17A and G-CSF in comparison to control children." (PMID 37013538, 2023). "In detail, we detected spike S1- and S2-reactive IFN-γ and/or IL-2 secreting cells in 61.1% (11/18) and 72.2% (13/18) of hoVac KTRs after second COVID-19 vaccination." (PMID 37063863, 2023). "In COVID-19, IL-2 is one of the signature interleukins of the exaggerated inflammatory response that has been observed in patients with a more severe disease." (PMID 37175392, 2023). "Inhibitors of janus kinase (JAK) block the intracellular signalling pathways of cytokines that promote and sustain inflammation in severe COVID-19, including IL-2, IL-6, IL-10, GM-CSF and IFNγ." (PMID 36941580, 2023). "On the counter, in a study on 115 patients, the blood sample tests demonstrated that serum IL-2 was lower in patients with severe or moderate COVID-19 than individuals with asymptomatic and mild COVID-19." (PMID 37649897, 2023). "We show that a core set of co-regulated immune response genes display a pronounced and specific inverted expression profile from original discovery in an anti-inflammatory context (T1D patients treated with low-dose IL-2) compared to COVID-19 patients." (PMID 37700317, 2023). "Patients with severe COVID-19 showed significant increases in cytokines, including IL-2, IL-7, IL-10, GSCF, IP10, MCP-1, MIP1A and TNF-α, with the characteristics of a cytokine storm." (PMID 37112613, 2023). "Cytokine concentration (TNF-alfa, IFN-gamma, IL-2, IL-4, IL-6, and IL-10) increased greatly after in vitro exposure to the COVID-19 vaccine." (PMID 37686102, 2023). "The inclusion criteria were the original studies on the role of the IL-2 cytokine family in COVID-19." (PMID 37649897, 2023). "We observed a markedly reversed regulation of the core genes of this NF-κB-regulated transcriptional network in the context of COVID-19 versus low-dose IL-2 treatment in T1D." (PMID 37700317, 2023). "Our results indicated that serum levels of IL-2, IL-4, IL-6, and IL-10 were increased in COVID-19 patients compared to healthy subjects." (PMID 35540724, 2022). "Inhibits JAK3, JAK1, JAK2, and to a lesser extent TYK2 and inhibits receptor signaling through pairs of JAK2 and because it can suppress the production of different cytokines, such as IL-2, IL-7 and IL-6 can used for patients with COVID-19." (PMID 36111104, 2022). "Compared with those in mild disease, levels of inflammatory factors such as IL-2, IL-12 (p40), and IL-10 were increased in moderate disease, and these factors have been previously reported to be increased in patients with COVID-19." (PMID 35254122, 2022).